ANXA6 (annexin A6)
Diseases named in the same sentence as ANXA6 in open-access papers (continued):
Sharing a sentence is not in itself a finding about the gene and the disease.
muscular dystrophy (10 papers, 2017 to 2025). Muscular dystrophy (MD) refers to a group of more than 30 genetic diseases characterized by progressive weakness and degeneration of the skeletal muscles that control movement. "Anxa6, the gene encoding annexin A6, was discovered as a genetic modifier of muscular dystrophy, including genetic signals that implicated annexin A6 in cardiac function in a mouse model of muscular dystrophy." (PMID 38050701, 2024). "Anxa6 encodes the membrane-associated protein annexin A6 and was identified as a genetic modifier of muscle repair and muscular dystrophy." (PMID 35866481, 2022). "Genetic manipulation of Ltbp4 in dystrophic muscle also directly modulated sarcolemmal resealing, and Ltbp4 alleles acted in concert with Anxa6, a distinct modifier of muscular dystrophy." (PMID 29065150, 2017). "The importance of ANXA6 in muscle cell plasma membrane repair was recognized when mutations of the ANXA6 gene were found to negatively impact the phenotype of dysferlinopathy (a group of rare muscular dystrophies with recessive mutations in the dysferlin gene)." (PMID 32326222, 2020). "The role played by ANXA6 as a genetic modifier of muscular dystrophies is definitely the most described." (PMID 34067866, 2021). "ANXA6N32 dramatically impairs translocation of the full-length ANXA6 to the membrane disruption site, disrupts the protein scaffold that is pivotal for membrane resealing, and enhances muscular dystrophy." (PMID 34067866, 2021). "Other genetic modifiers of muscular dystrophy also interfered with AnxA6 recruitment for sarcolemma resealing." (PMID 33810523, 2021). "Additionally, we evaluated the response to a resealing protein, recombinant annexin A6, which was previously identified as a genetic modifier of muscular dystrophy and a potential therapeutic target." (PMID 38050701, 2024). "Genetic modifiers on the DBA/2 genetic background, including osteopontin (Spp1), synonymous variant in Annexin A6 (Anxa6) exon 1, and polymorphisms in the coding region of the latent TGF-β-binding protein 4 gene (Ltbp4), generate a more severe muscular dystrophy mouse model." (PMID 36388984, 2022). "Strikingly, in a mouse model of muscular dystrophy, a naturally occurring AnxA6 splice variant created a truncated AnxA6 protein lacking four of the eight annexin repeats." (PMID 33810523, 2021). "The importance of AnxA6 in membrane repair has been recently reinforced by the demonstration that the treatment with recombinant AnxA6 protects against acute muscle injury in wild-type mice and reduced the level of serum creatinine kinase, a biomarker of disease, in a model of muscular dystrophy." (PMID 32708200, 2020). "Nevertheless, AnxA6 has been identified as being a genetic modifier of muscular dystrophy." (PMID 32708200, 2020). "Promisingly, recombinant annexin A6 injected into 5XFAD and APP-NLGF knock-in mouse brains shows the ability to bind to the membranes of DNs around amyloid plaques suggesting that, like in muscular dystrophy, annexin A6 protein could be investigated as a therapeutic." (PMID 40411591, 2025). "Injection of recombinant ANXA6 may be foreseen as therapeutic treatment of muscular dystrophies." (PMID 34067866, 2021). "Hitherto, no muscular dystrophy has been linked to AnxA6 deficiency, but the etiology of numerous muscular dystrophies remains unknown." (PMID 32708200, 2020).
melanoma (9 papers, 2018 to 2023). A malignant, usually aggressive tumor composed of atypical, neoplastic melanocytes. "Low expressions of AXNA6 was reported in melanoma malignancy and epithelial carcinoma, whereby, the overexpression of ANXA6 leads to tumor suppression effects in A431 cells." (PMID 31877708, 2019). "Other studies have unambiguously demonstrated that AnxA6 may be useful to detect minimal residual disease in B-lineage acute lymphoblastic leukemia, the progression of melanomas and squamous cervical cancer carcinogenesis." (PMID 32784650, 2020). "However, elevated ANXA6 levels have been found in the progression of pancreatic cancer, female thyroid cancer, squamous cervical cancer, ovarian cancer, esophageal adenocarcinoma, and melanoma." (PMID 37129645, 2023).
pancreatic ductal adenocarcinoma (7 papers, 2018 to 2024). An infiltrating adenocarcinoma that arises from the epithelial cells of the pancreas. "ANXA6 enrichment in CAF-derived exosomes is reflected in the serum-derived exosomes of pancreatic ductal adenocarcinoma patients, where elevated ANXA6 levels are associated with higher tumor grades and poor clinical outcomes." (PMID 32957712, 2020). "Inhibition of CD9 expression in pancreatic ductal adenocarcinoma inhibited the uptake of annexin A6 extracellular vesicles into cancer cells and impaired annexin A6-induced cell migration and EMT processes via the p38 MAPK pathway." (PMID 38389703, 2024). "ANXA6-EVs, derived from cancer-associated stromal fibroblasts (CAF), promotes tumor cell invasiveness in pancreatic ductal adenocarcinoma, and the blockade of CD9 impairs the uptake of ANXA6-EVs by pancreatic ductal adenocarcinoma cells." (PMID 37129645, 2023). "In pancreatic ductal adenocarcinoma (PDA) cells in vitro, loss of ANXA6 in CAF altered the development of ANXA6, LRP1, and TSP1 complexes, suppressing PDA and metastasis." (PMID 37124542, 2023). "The proteomic stromal signature of pancreatic ductal adenocarcinoma (PDA) shows a contribution of the annexin A6/LDL receptor-related protein 1/thrombospondin 1 (ANXA6/LRP1/TSP1) complex in tumour cell crosstalk." (PMID 29462943, 2018). "In pancreatic ductal adenocarcinoma (PDA), cancer-associated fibroblasts (CAF)-derived extracellular vesicles containing the complex ANXA6/LRP1/TSP1 enhanced tumor aggressiveness, and ANXA6 was crucial to promote aggressive phenotypes, invasion in vitro, and metastasis formation in vivo." (PMID 36247003, 2022).
osteosarcoma (6 papers, 2019 to 2025). A usually aggressive malignant bone-forming mesenchymal neoplasm, predominantly affecting adolescents and young adults. "ANXA6 is highly expressed in osteosarcoma, and regulates mineralization during carcinogenesis in osteosarcoma." (PMID 37129645, 2023). "In control variants without apigenin, in resting osteoblastic hFOB 1.19 (upper left side), and osteosarcoma Saos-2 (upper left side) cells, AnxA6 was uniformly distributed." (PMID 36361965, 2022). "Bioinformatics analysis identified six exosome‐associated osteosarcoma genes (WNT5A, GCA, ANXA6, BIRC5, IL1β, and ARPC3) that could serve as potential biomarkers." (PMID 40616392, 2025). "AnnexinA6 (AnxA6), a Ca2+-dependent phospholipid-binding protein, has been extensively reported as an essential target in mineralization-related diseases such as osteoporosis, osteoarthritis, atherosclerosis, osteosarcoma, and calcific aortic valve disease." (PMID 37727505, 2023). "In the present study, using biochemical methods and microscopy techniques, we investigated novel roles of Src kinase and ROCK signaling pathways in the regulation of the mineralization of human osteosarcoma Saos-2 cells, with special emphasis on the role of AnxA6." (PMID 31212828, 2019). "Other genes, including WNT5A (AUC = 0.935), GCA (AUC = 0.922), ANXA6 (AUC = 0.909), ARPC3 (AUC = 0.909), and IL1β (AUC = 0.766) also exhibited heterogeneous levels of predictive precision for detecting osteosarcoma." (PMID 40616392, 2025). "The expression profiles of six core genes (WNT5A, GCA, ANXA6, BIRC5, IL1β, and ARPC3) were contrasted between the control and osteosarcoma groups." (PMID 40616392, 2025). "This study describes the apigenin effect on the proliferation as well as AnxA6- and TNAP-mediated mineralization of human fetal osteoblastic hFOB 1.19 and osteosarcoma Saos-2 cells." (PMID 36361965, 2022). "Stimulation for mineralization increased the concentration of both annexins, AnxA6 and AnxA2, in the sub-membrane region and their co-localization with TNAP in strongly mineralizing Saos-2 osteosarcoma cells." (PMID 33924370, 2021). "In this report, apigenin potency to modulate annexin A6 (AnxA6)- and TNAP-mediated osteoblast mineralization was explored using three cell lines: human fetal osteoblastic hFOB 1.19, human osteosarcoma Saos-2, and human coronary artery smooth muscle cells HCASMC." (PMID 36361965, 2022). "In the present study, we have examined the effect of apigenin on AnxA6- and TNAP-mediated osteoblast mineralization using three cellular models: human fetal osteoblastic hFOB 1.19, human osteosarcoma Saos-2, and human coronary artery smooth muscle cells HCASMC." (PMID 36361965, 2022). "Vinculin, as F-actin, also does not co-localize with AnxA6 in mineralizing osteosarcoma Saos-2 cells." (PMID 31212828, 2019).
ovarian carcinoma (6 papers, 2019 to 2023). A malignant neoplasm originating from the surface ovarian epithelium. "ANXA2, a gene in the same family as ANXA6, is frequently up-regulated in various tumors, such as ovarian cancer." (PMID 36712880, 2022). "Upregulation of ANXA6 in ovarian cancer promotes cell proliferation." (PMID 37129645, 2023). "Both databases showed that ANXA2, ANXA3, ANXA8, and ANXA11 mRNA expression levels were upregulated in ovarian cancer compared with normal tissues, while ANXA5,ANXA6, and ANXA7 mRNA expression levels were downregulated." (PMID 31474227, 2019). "In addition, the expression levels of ANXA1, ANXA4, ANXA5, ANXA6, ANXA7 and ANXA13 were lower in ovarian cancer than in the normal controls." (PMID 31474227, 2019).
nasopharyngeal carcinoma (5 papers, 2020 to 2025). A carcinoma arising from the nasopharyngeal epithelium. "Three ANXA6 SNPs (rs4346760, rs4958897, and rs3762993) facilitated the occurrence of nasopharyngeal carcinoma." (PMID 36998449, 2023). "ANXA6 promoted autophagy by inhibiting the PI3K/AKT/mTOR signaling pathway in nasopharyngeal carcinoma." (PMID 35456441, 2022). "These include Annexin A6 (ANXA6) and CD146/Melanoma cell adhesion molecule (MCAM), which were reported to promote radioresistance in nasopharyngeal carcinoma and glioblastoma multiforme, respectively." (PMID 40497995, 2025).
psoriasis (5 papers, 2011 to 2023). An autoimmune condition characterized by red, well-delineated plaques with silvery scales that are usually on the extensor surfaces and scalp. "The gene encoding AnxA6 has been reported to be one of the psoriasis susceptibility genes in the Chinese Han population." (PMID 36498634, 2022). "Certain SNPs in the Anxa6 locus have been linked to psoriasis, while another polymorphism in the Anxa6 coding region causes a dominant-negative deletion mutant in a mouse model for muscle dystrophy that interferes with membrane repair." (PMID 33810523, 2021). "However, to date, no study has evaluated the role of the rs11960458 polymorphism of AnxA6 in lipid changes following MTX treatment of psoriasis." (PMID 36498634, 2022). "Clearly, further fine mapping is necessary to identify the causal variant that exerts opposing effects on AD and psoriasis, but we speculate that ANXA6 might be a switch-point differentiating AD from psoriasis that reflects the importance of calcium-dependent effects in keratinocyte differentiation." (PMID 25574825, 2015). "We further identified previously unreported pleiotropic alleles with opposing effects on atopic dermatitis and psoriasis risk in PRKRA and ANXA6/TNIP1." (PMID 25574825, 2015). "Considering the role of AnxA6 in lipometabolism, a relationship may exist between AnxA6 and the blood lipid profiles of psoriasis patients during MTX treatment." (PMID 36498634, 2022). "Therefore, we sought to determine the impact of the rs11960458 genotype on the expression of the AnxA6 protein, and the role of this SNP in the lipometabolism of psoriasis patients following MTX treatment." (PMID 36498634, 2022). "However, the correlation of AnxA6 polymorphism with lipometabolism has never been studied in psoriasis." (PMID 36498634, 2022). "The most highly significant variant at 5q33.1 (rs17728338) shows opposing effects on AD and psoriasis (MNM p = 3.96 × 10−38) and lies 2 kb upstream of ANXA6 (MIM 114070) and 8 kb downstream of TNIP1 (MIM 607714)." (PMID 25574825, 2015). "Two of the loci displaying opposing effects (ANXA6/TNIP1 and PRKRA) have not previously been reported in association with psoriasis and/or AD." (PMID 25574825, 2015).
bladder cancer (4 papers, 2021 to 2023). "Evidence from bioinformatics analysis demonstrated that ANXA6 is downregulated in bladder cancer." (PMID 37129645, 2023). "In addition, silencing YAP could counteract the effects of ANXA6-EVs on paclitaxel resistance and cancer aggressiveness in bladder cancer cells." (PMID 37129645, 2023). "The high expression of ABCB9, SPTBN2, GULP1, IGF1, P4HB, NES and DPYSL2 and the low expression of ANXA6, OAS1, RAD9a, DNASE2B and FANCF would be beneficial to the prognosis of bladder cancer patients." (PMID 37845668, 2023). "The expression of ANXA1, ANXA2, ANXA3, ANXA5, ANXA6, ANXA8, and ANXA13 was closely related to basal-subtype bladder cancer, while the expression of ANXA4, ANXA9, ANXA10, and ANXA11 was closely related to luminal-subtype BC." (PMID 34484309, 2021). "ANXA1, ANXA2, ANXA3, ANXA5, ANXA6, ANXA7, and ANXA9 had prognostic value in bladder cancer." (PMID 34484309, 2021). "We used TCGA data to find that in addition to ANXA1 and ANXA2, other ANXA family proteins (ANXA3, ANXA5, ANXA6, and ANXA9, which have not been studied) are also closely related to the prognosis of bladder cancer." (PMID 34484309, 2021).
hepatocellular carcinoma (4 papers, 2020 to 2024). A malignant tumor that arises from hepatocytes. "Herein we focus on the biological function of AnxA6 SUMOylation in hepatocellular carcinoma (HCC) progression." (PMID 38566133, 2024). "Similarly, ANXA6 is downregulated in human hepatocellular carcinoma." (PMID 37129645, 2023). "Firstly, we detected the expression level of RHOU, AnxA6 and SENP1 protein in mouse orthotopic hepatoma tissues." (PMID 38566133, 2024).
Obesity (4 papers, 2018 to 2025). Accumulation of substantial excess body fat. "Finally, in brown fat, which is quite distinct from other fat tissues as its main function is to produce heat, AnxA6 protein amounts remained unchanged in obesity." (PMID 31337068, 2019). "Remarkably, fat depot distribution of AnxA6 changed in obesity." (PMID 31337068, 2019). "In fact, pre-adipocyte proliferation is increased in obesity, and elevated AnxA6 levels in white adipose tissue of obese mice might reflect a requirement for AnxA6 in molecular pathways governing adipose proliferation." (PMID 30110341, 2018). "We also analysed hepatic Anxa6 mRNA expression in mouse models subjected to 24 h fasting, high‐fat diet (HFD), and with genetic background of obesity (ob/ob mice) (GSE85439)." (PMID 40802799, 2025). "In obese animals, batosomes are enriched with proteins involved in signal transduction, cell communication, the immune response, inflammation, thermogenesis, and as obesity biomarkers including UCP1, Glut1, MIF, annexin A6, CD14, and ceruloplasmin." (PMID 36142750, 2022).
osteoporosis (4 papers, 2022 to 2025). A condition of reduced bone mass, with decreased cortical thickness and a decrease in the number and size of the trabeculae of cancellous bone (but normal chemical composition), resulting in increased fracture incidence. "We found that the expression of AnxA2, AnxA5 and AnxA6 was distributed along the edge of cancellous bone where the osteoblasts were distributed, and their expression was lower in the osteoporosis group than in the sham group." (PMID 37940665, 2023). "Growing evidence indicates that the abnormal expression of AnxA6 in osteoblasts and smooth muscle cells leads to some pathological processes such as the development of osteoporosis and atherosclerosis." (PMID 36555344, 2022).
acute lymphoblastic leukemia (3 papers, 2020 to 2023). Leukemia with an acute onset, characterized by the presence of lymphoblasts in the bone marrow and the peripheral blood. "This is also supported by previous reports showing that detection of AnxA6 may be useful in identifying minimal residual disease in B-lineage acute lymphoblastic leukemia, and to stratify non-invasive cervical intraepithelial neoplasia from invasive squamous cervical cancer." (PMID 32298357, 2020).
breast tumors (3 papers, 2019 to 2020). "This is consistent with our earlier reports showing that low AnxA6 expression is associated with poor overall survival of patients with basal-like breast tumors and the reported reduced expression of AnxA6 in malignant forms of several solid tumor types." (PMID 32298357, 2020). "We and others have also demonstrated that treatment of breast tumor cells with TKIs, nonselective Ca2+ channel blockers, and the DNA methyltransferase (DNMT) inhibitors 5-aza-2′-deoxycytidine or 5-aza-cytidine led to AnxA6 upregulation." (PMID 32784650, 2020).
cardiomyopathy (3 papers, 2013 to 2024). A disease of the heart muscle or myocardium proper. "This, in addition to the impaired self-renewal capacity due to an alternative splicing of the Annexin A6—ANXA6 gene, overall contributes to a faster progression of disease and early cardiomyopathy." (PMID 39535998, 2024).
Hypoglycemia (3 papers, 2018 to 2025). A decreased concentration of glucose in the blood. "This pointed at ANXA6 deficiency to trigger stress‐induced hypoglycaemia due to deficiencies in the utilization of alternative sources for glucose production, such as GNG." (PMID 40802799, 2025). "Although exogenous glucose administration or restoration of hepatic ANXA6 expression rescued the survival of ANXA6 knockout mice after PHx, persistent hypoglycemia resulted from impaired alanine-dependent gluconeogenesis in ANXA6-deficient hepatocytes." (PMID 37129645, 2023). "Altogether, these results demonstrate that Anxa6−/− mice were unable to maintain blood glucose levels under fasting conditions, manifested as significant hypoglycaemia immediately after food deprivation." (PMID 40802799, 2025). "The robust fasting‐induced hypoglycaemia observed in Anxa6−/− mice persisted despite the efficient mobilisation of elevated hepatic glycogen reserves at elevated degradation rates from the onset of the fasting state in these animals." (PMID 40802799, 2025). "Thus, based on these analyses, impaired ability to drive hepatic GNG via alanine appears a likely factor for the development of hypoglycaemia in fasted Anxa6−/− mice." (PMID 40802799, 2025). "However, given the abnormal glycogen accumulation in livers of HFD-fed AnxA6 KO-mice, prolonged starvation could have resulted in hypoglycemia." (PMID 30110341, 2018).
osteoarthritis (3 papers, 2021 to 2023). A noninflammatory degenerative joint disease occurring chiefly in older persons, characterized by degeneration of the articular cartilage, hypertrophy of bone at the margins and changes in the synovial membrane. "Moreover, AnxA6 overexpression attenuated mechanical pain, indicating therapeutic potential to inhibit chronic mechanical pain commonly associated with osteoarthritis." (PMID 33810523, 2021). "In studies mimicking osteoarthritis, knee cartilage destruction after IL-1β injection or partial meniscectomy was strongly reduced in AnxA6 KO-mice." (PMID 33810523, 2021). "The ability of AnxA6 to influence the organization of cholesterol-rich plasma membrane microdomains on neuronal cells also appears relevant in osteoarthritis." (PMID 33810523, 2021). "Furthermore, in articular chondrocytes from control animals, AnxA6 associates with the plasma membrane to interfere with Wnt/b-catenin signaling, affecting crosstalk with NFκB signaling, catabolic and inflammatory events, all of which contributing to cartilage degradation in osteoarthritis." (PMID 33810523, 2021).